SCN2A (sodium voltage-gated channel alpha subunit 2)
Diseases named in the same sentence as SCN2A in open-access papers (continued):
Sharing a sentence is not in itself a finding about the gene and the disease.
meningioma (1 paper, 2020). A generally slow growing tumor attached to the dura mater. "Six potentially pathogenic mutations in PHRF1, ZC3H12B, H2AFV, DNAJC13, DNAH8, SCN2A were non-recurrent; however, given the modest sample size it is difficult to fully evaluate the importance of these variants in the meningioma progression." (PMID 32724039, 2020).
mental disorder (1 paper, 2023). A disease that has its basis in the disruption of mental process. "Finally, the mature stage T5 was enriched for synaptic signaling genes (FDR = 5 × 10–16; e.g., CADPS2 and SNAP25) and regulation of membrane potential (FDR = 3 × 10–11; e.g., RIMS1 and SCN2A), and was most specifically marked by RBFOX1, an RNA-binding protein implicated in many mental disorders." (PMID 36865235, 2023).
myoclonic epilepsy (1 paper, 2022). A group of epilepsy syndromes in which myoclonic seizures are a prominent feature. "However, mutational analysis showed that frameshift mutation in exon 26 of SCN2A can lead to premature stop codon which can affect the protein structure leading to myoclonic epilepsy." (PMID 35136380, 2022).
prion disease (1 paper, 2021). A transmissible disease that is caused by a protein that is able to induce abnormal folding of normal cellular proteins, leading to characteristic spongiform brain changes, which are associated with neuronal loss without an inflammatory response. "PrPSc formation inhibition is a major target for therapeutic intervention in prion disease; thus, ScN2a cells continuously producing PrPSc are valuable models for detecting anti-prion activity." (PMID 34043140, 2021).
neurodevelopmental disorder (28 papers, 2015 to 2025). A behavioral and cognitive disorder with onset during the developmental period that involves impaired or aberrant development of intellectual, motor, or social functions. "For example, disrupted interactions between Densin-180 and PP1α as well as changes in the Scn2a-associated proteome have been linked to neurodevelopmental disorders." (PMID 40771565, 2025). "One gene of particular interest is Scn2a, which encodes the alpha subunit of the voltage-gated Na+ channel 1.2 (Nav1.2), is highly linked to neurodevelopmental disorders including ASD20–22." (PMID 39257993, 2024). "Subsequently, it has been shown that pathogenic variants of SCN2A/NaV1.2 cause a range of neurodevelopmental disorders, including DEE of varying severity." (PMID 37654020, 2024). "Pathogenic variants in SCN2A are associated with a spectrum of epileptic and neurodevelopmental disorders, i.e., SeLFNIE, ID, and ASD, presenting an autosomal dominant inheritance." (PMID 39596607, 2024). "Pathogenic variants in SCN2A are one of the most common causes of neurodevelopmental disorders." (PMID 39596607, 2024). "Deleterious variation in the SCN2A gene is associated with neurodevelopmental disorders." (PMID 38151324, 2023). "However, the current rates of SCN2A mutations in both ASD and other neurodevelopmental disorder populations are likely underestimated, and the incidence is expected to increase significantly as genetic testing for these patients becomes more widespread." (PMID 32264956, 2020). "SCN2A has been recognized as an important factor in a series of neurodevelopmental disorders." (PMID 32649035, 2020).
neurological disorders (15 papers, 2015 to 2025). "Among these, the genes most frequently associated with inherited forms of neurological disorders encode for brain Na+ channels Nav1.1 (SCN1A) and Nav1.2 (SCN2A)." (PMID 26236192, 2015). "This narrative review summarizes some of the most recent therapeutic approaches approved or under investigation for the treatment of SCN1A-, SCN2A- and SCN8A-related neurologic disorders." (PMID 41515912, 2025). "We next compared our genes to gene sets of ASD or other neurological disorders and found that CHD8, DYRK1A, GRIN2B, MBD5 and SCN2A overlapped with the ASD gene sets (FDR ≤ 0.1) reported in previous large-scale ASD studies." (PMID 32193494, 2020).
psychiatric disorder (6 papers, 2014 to 2025). A disorder characterized by behavioral and/or psychological abnormalities, often accompanied by physical symptoms. "Sodium channel disruptions, such as mutations in SCN2A, may play an important role in psychiatric disorders." (PMID 24650168, 2014). "Genetic variants in the SCN2A gene are also important in ASD; they can play a significant role in psychiatric disorders." (PMID 35205412, 2022). "However, SCN2A‐related disorders manifest in a broad clinical neuropsychiatric spectrum, including distinct neurological and psychiatric disorders." (PMID 40884529, 2025).
infection (4 papers, 2011 to 2023). The state of being infected such as from the introduction of a foreign agent such as serum, vaccine, antigenic substance or organism. "Cell based research utilizes cell lines such as N2a (mouse neuroblastoma cells) to assess the ability of a given therapeutic agent to either prevent infection of the cells by prions, or to clear PrPSc from a chronically infected cell line like ScN2a." (PMID 23738120, 2012). "Because N2a cells show heterogeneous potential for infection with prions, even in clonal populations of cells, we performed further subcloning of the ScN2a-Sho cells in order to isolate subclones that were more uniformly infected." (PMID 22163178, 2011).
metabolic disorders (3 papers, 2023 to 2025).
tumour (3 papers, 2020 to 2024). "The results of the UALCAN database had showed that SCN2A/4A/5A/8A mRNA were highly expressed in tumour tissues, while SCN1A/7A/11A mRNA were expressed at low levels (p < 0.05), furthermore, the expression of SCN4A and SCN7A had the similar levels in microarray analysis result." (PMID 35126466, 2021). "Some candidate markers, such as IRX3, PDX1 and SCN2A, have not been found to be associated with tumours." (PMID 32649035, 2020).
cancer (2 papers, 2016 to 2025). A tumor composed of atypical neoplastic, often pleomorphic cells that invade other tissues. "When delivered to HEK293T cells, an easy-to-transduce immortalized cancer cell line with a relatively permissive chromatin environment, both promoter- and enhancer-targeting gRNAs upregulated SCN2A." (PMID 41278953, 2025). "On the other hand, “hub genes” of four other modules contain POU2F3 (↑), CENPH (↑), PCSK6 (↑) and HERC2 (↑), BCAR3 (↑), DOHH (↑), NLK (↑), SCN2A (↑), CACNA2D3 (↓) and CTNND2 (↓), which were commonly reported related to cancer." (PMID 27602771, 2016).
genetic disorders (1 paper, 2022). "Differs from the high-frequency genes, other causative genes (ARX, SCN2A, etc.)were only found in <3% of the cases with genetic disorders, respectively." (PMID 35330882, 2022).
SCN2A also shares sentences with these, for which no sentence is quoted: infantile epileptic encephalopathy (8 papers); movement disorder (5); benign familial infantile seizure (4); developmental and epileptic encephalopathy, 11 (4); focal epilepsy (4); Alzheimer disease (3); brain disorder (3); febrile seizures (3); myoclonic atonic epilepsy (3); absence seizures (2); Angelman syndrome (2); biotinidase deficiency (2); central nervous diseases (2); cervical cancer (2); Chorea (2); Choreoathetosis (2); depression (2); early onset epilepsy (2); generalized (genetic) epilepsy (2); microcephaly (2); migraine (2); neurodegenerative disease (2); ocular hypertension (2); status epilepticus (2); 22q11.2 deletion syndrome (1); amyotrophic lateral sclerosis (1); Aphasia (1); Athetosis (1); atrial fibrillation (1); Atrophy (1).
A further 64 diseases each share a sentence with SCN2A in 1 paper.